TFDP2 (transcription factor Dp-2)
Description:
Can stimulate E2F-dependent transcription. Binds DNA cooperatively with E2F family members through the E2 recognition site, 5'-TTTC[CG]CGC-3', found in the promoter region of a number of genes whose products are involved in cell cycle regulation or in DNA replication. The TFDP2:E2F complex functions in the control of cell-cycle progression from G1 to S phase. The E2F1:DP complex appears to mediate both cell proliferation and apoptosis. Blocks adipocyte differentiation by repressing CEBPA binding to its target gene promoters.
Synonyms: DP2; Dp-2
Tractability: PROTAC: ubiquitination databases record sites on it; a small molecule that binds it is known.
Target class: Transcription factor
Gene: Protein-coding gene on chromosome 3 (141,944,428 to 142,149,544, reverse strand). Ensembl gene ENSG00000114126.
Subcellular location: Nucleus
Subcellular location (Human Protein Atlas): Nucleoplasm; Mitotic spindle; Vesicles
Pathways (Reactome):
Cell Cycle: Cyclin A:Cdk2-associated events at S phase entry; Cyclin D associated events in G1; Cyclin E associated events during G1/S transition; G0 and Early G1; G1/S-Specific Transcription; Inhibition of replication initiation of damaged DNA by RB1/E2F1; Transcription of E2F targets under negative control by DREAM complex; Transcription of E2F targets under negative control by p107 (RBL1) and p130 (RBL2) in complex with HDAC1
Cellular responses to stimuli: Oncogene Induced Senescence; Oxidative Stress Induced Senescence
Gene expression (Transcription): Transcriptional Regulation by E2F6
Programmed Cell Death: Activation of NOXA and translocation to mitochondria; Activation of PUMA and translocation to mitochondria
Signal Transduction: Pre-NOTCH Transcription and Translation; SMAD2/SMAD3:SMAD4 heterotrimer regulates transcription
Developmental Biology: Transcriptional regulation of granulopoiesis
Disease: Defective binding of RB1 mutants to E2F1,(E2F2, E2F3)
Gene Ontology:
Molecular function: DNA-binding transcription activator activity, RNA polymerase II-specific; protein binding; protein domain specific binding; RNA polymerase II transcription regulatory region sequence-specific DNA binding; transcription factor binding; DNA-binding transcription factor activity, RNA polymerase II-specific
Biological process: negative regulation of DNA-templated transcription; positive regulation of transcription by RNA polymerase II; regulation of DNA-templated transcription; regulation of transcription by RNA polymerase II; regulation of cell cycle; regulation of gene expression
Cellular component: nucleoplasm; RNA polymerase II transcription regulator complex; chromatin; DRM complex; nucleus; transcription regulator complex
Genetic constraint (gnomAD): Loss-of-function variants: 13 observed, 46.7 expected, observed/expected ratio (o/e) 0.28, 90% interval 0.18 to 0.44. The upper end of that interval is the gene's LOEUF score, 0.44, which puts it in group 1 of 6, group 1 being the genes least tolerant of losing a copy. Missense variants: 328 observed, 466.35 expected, observed/expected ratio (o/e) 0.7, 90% interval 0.64 to 0.77. Synonymous variants: 158 observed, 180.26 expected, observed/expected ratio (o/e) 0.88, 90% interval 0.77 to 1.
Homologues: Orthologues: macaque TFDP2 (99% identical), chimpanzee TFDP2 (99% identical), pig TFDP2 (99% identical), guinea pig TFDP2 (96% identical), dog TFDP2 (96% identical), mouse Tfdp2 (95% identical), rabbit TFDP2 (94% identical), rat Tfdp2 (90% identical), tropical clawed frog tfdp2 (63% identical), zebrafish tfdp2 (59% identical), Drosophila melanogaster Dp (39% identical), Caenorhabditis elegans dpl-1 (34% identical). Paralogues in human: TFDP1 (59% identical), TFDP3 (46% identical).
Diseases named in the same sentence as TFDP2 in open-access papers:
TFDP2 is named in the same sentence as 17 diseases in open-access papers, as found by Europe PMC text mining. Sharing a sentence is not in itself a finding about the gene and the disease. The quoted sentences say what the papers report.
hepatocellular carcinoma (3 papers, 2016 to 2021). A malignant tumor that arises from hepatocytes. "In hepatocellular carcinoma (HCC), c-Myc represses miR-122 expression that in turn indirectly inhibits c-Myc transcription by targeting the transcription factor Dp-2 (Tfdp2) and E2F transcription factor 1 (E2f1), which are essential for tumor development." (PMID 33672261, 2021).
leukemia (3 papers, 2014 to 2021). A malignant (clonal) hematologic disorder, involving hematopoietic stem cells and characterized by the presence of primitive or atypical myeloid or lymphoid cells in the bone marrow and the blood. "ACER3 coregulates cell proliferation and survival with ACER2 and plays an important role in leukemia development; while TCL6 is associated with clinical outcomes of B-cell acute lymphoblastic leukemia patients; TFDP2 plays core roles in apoptosis and cell proliferation." (PMID 34722498, 2021).
chronic kidney disease (1 paper, 2020). Impairment of the renal function secondary to chronic kidney damage persisting for three or more months. "The whole-genome analysis report for chronic kidney disease shows that Tfdp2 is related to renal function and CKD." (PMID 33664736, 2020).
colorectal cancer (1 paper, 2020). A primary or metastatic malignant neoplasm that affects the colon or rectum. "Hypermethylated genes were observed across the four cancers, such as ZNF655, RB1, and TFDP2, which have previously been reported to be epigenetic diagnostic biomarkers for various cancers (including breast and colorectal cancers)." (PMID 33143142, 2020).
liver fibrosis (1 paper, 2020). "Among six potential transcription factors (conserved between mice and humans) that bind at the proximal promoter region of the identified BCL2 gene, we focused on c-MYC as it is known to modulate liver fibrosis and is regulated by miR-122 through E2F1 and TFDP2 in mouse hepatic cells." (PMID 32650615, 2020).
papillary carcinoma (1 paper, 2021). A malignant epithelial neoplasm characterized by a papillary growth pattern. "TFDP2 was decreased in human papillary carcinoma tissue, and its expression can be altered by CDDP treatment." (PMID 34434692, 2021).
renal fibrosis (1 paper, 2020). A final common manifestation of a wide variety of chronic kidney diseases characterized by glomerulosclerosis and tubulointerstitial fibrosis. "To evaluate the expression and function of Tfdp2 in renal fibrosis, we first transiently transfected Tfdp2 siRNA into mRTECs to down-regulate the expression of Tfdp2 in mRTECs." (PMID 33664736, 2020). "Our study indicates that BM-MSC attenuates cisplatin-induced renal fibrosis by regulating miR-146a-5p/Tfdp2 axis in mRTECs." (PMID 33664736, 2020). "Our study provides the first evidence that the protection of BM-MSCs on renal fibrosis via miR-146a-5p/Tfdp2 axis in renal tubular epithelial cells." (PMID 33664736, 2020). "Our results indicate that BM-MSC attenuates cisplatin-induced renal fibrosis by regulating the miR-146a-5p/Tfdp2 axis in mRTECs." (PMID 33664736, 2020). "In addition, the contribution of miR-146a-5p/Tfdp2 axis in renal fibrosis is worth further investigating and verifying in human kidney tissues." (PMID 33664736, 2020). "In addition, the relevance of Tfdp2 in renal fibrosis was confirmed in cisplatin-treated mouse kidney tissues by the IHC staining." (PMID 33664736, 2020). "Additionally, the function of miR-146a-5p/Tfdp2 axis in renal fibrosis should be further investigated in preclinical and clinical studies, which might be a potential therapeutic target for renal fibrosis." (PMID 33664736, 2020).
tumor (10 papers, 2015 to 2025). "In the same context, miR-103 was found to be downregulated in tumor samples from spleen and liver of infected chickens, where it targets cyclin E1 and the transcription factor Dp-2, which normally causes suppression of cell migration and tumor formation." (PMID 27800484, 2016). "In conclusion, gga-miR-103-3p targets the CCNE1 and TFDP2 genes, and suppresses cell migration, which indicates that it might play an important role in MD tumor transformation." (PMID 26935418, 2016). "For instance, high expression of TFDP2 (Transcription Factor Dp‐2), has been documented in HPV(+)HNSCC and HPV(+)CC compared with HPV(−) tumours, highlighting its roles." (PMID 38279874, 2024). "mir-122 is a tumor suppressor that is directly inhibited by MYCC and that, in turn, represses MYCC via its repression of E2f1 and Tfdp2." (PMID 29880060, 2018). "Except for few being chromatin regulators (CGBP, MBD2, and DNMT1), all of these TFs were found to have tumor suppressor functionality (BRCA1, E2F1&2&5&7, EGR1-4, FLI1, NRF1, TFDP2, and STAT1), or indirectly mediate the suppression of tumorigenesis and tumor suppressor activity (SP4 and ZBTB33)." (PMID 29740534, 2018).
cancer (6 papers, 2020 to 2024). A tumor composed of atypical neoplastic, often pleomorphic cells that invade other tissues. "Survival analysis showed that hypermethylation of TFDP2, RBL1, and MYBL2 was associated with poor survival in most cancers." (PMID 35664326, 2022). "Meanwhile, survival analysis showed that hypermethylation of TFDP2, RBL1, and MYBL2 was associated with poor survival in most cancers." (PMID 35664326, 2022). "Of these, S100A8, CLEC10A, and TFDP2 exhibited significantly different expression profiles between cancer and precancerous stages." (PMID 34745098, 2021). "S100A8 and TFDP2 were identified as new gene markers of macrophages and were significantly different between cancer and precancerous stages." (PMID 34745098, 2021).
infection (1 paper, 2025). The state of being infected such as from the introduction of a foreign agent such as serum, vaccine, antigenic substance or organism. "On the other hand, wtAAV2 infection enriches the transcription factor TFDP2, which interacts with E2F proteins to regulate G1/S checkpoint entry." (PMID 40825038, 2025). "Host proteins enriched at cellular replication forks during infection included DNA processing factors such as GINS, TOP2A, PRIM1/2, RPA2 and XRCC1; DDR signaling proteins such as CSNK2A1/3; cell cycle regulator proteins such as TFDP2 and SFN1; as expected for cells undergoing replication stress." (PMID 40825038, 2025).
renal disease (1 paper, 2022). "Although the role of TFDP2 in the context of renal disease has not been reported, several genetic associations in or near TFDP2 have been reported in previous GWAS of eGFR and CKD." (PMID 36386835, 2022).
TFDP2 also shares sentences with these, for which no sentence is quoted: Alzheimer disease (1 paper); B-cell acute lymphoblastic leukemia (1); breast carcinoma (1); diffuse large B-cell lymphoma (1); neurological diseases (1); Type 2 diabetes (1).